SDR39U1 (short chain dehydrogenase/reductase family 39U member 1)
Description:
Putative NADP-dependent oxidoreductase.
Synonyms: C14orf124; HCDI
Tractability: Small molecule: a structure with a bound ligand is known. PROTAC: ubiquitination databases record sites on it; its protein half-life has been measured.
Gene: Protein-coding gene on chromosome 14 (24,439,766 to 24,442,905, reverse strand). Ensembl gene ENSG00000100445.
Subcellular location (Human Protein Atlas): Cytosol; Nucleoplasm
Gene Ontology:
Cellular component: mitochondrion; nucleus
Genetic constraint (gnomAD): Loss-of-function variants: 29 observed, 31.72 expected, observed/expected ratio (o/e) 0.91, 90% interval 0.68 to 1.25. The upper end of that interval is the gene's LOEUF score, 1.25, which puts it in group 5 of 6, group 1 being the genes least tolerant of losing a copy. Missense variants: 403 observed, 389.06 expected, observed/expected ratio (o/e) 1.04, 90% interval 0.95 to 1.12. Synonymous variants: 147 observed, 159.38 expected, observed/expected ratio (o/e) 0.92, 90% interval 0.81 to 1.06.
Homologues: Orthologues: macaque SDR39U1 (96% identical), dog SDR39U1 (88% identical), guinea pig SDR39U1 (86% identical), rabbit SDR39U1 (86% identical), rat Sdr39u1 (86% identical), mouse Sdr39u1 (85% identical), chimpanzee SDR39U1 (70% identical), tropical clawed frog sdr39u1 (58% identical), zebrafish sdr39u1 (55% identical), pig SDR39U1 (54% identical), Drosophila melanogaster CG8768 (42% identical).
Diseases named in the same sentence as SDR39U1 in open-access papers:
SDR39U1 is named in the same sentence as 5 diseases in open-access papers, as found by Europe PMC text mining. Sharing a sentence is not in itself a finding about the gene and the disease. The quoted sentences say what the papers report.
diabetes (1 paper, 2020). "In addition, we identified nine genes (CABIN1, CKS1B, C19orf60, SDR39U1, SLC31A1, DNAJA4, ZC3H8, OTUD3 and UBALD1) not previously associated with diabetes, but that are known to be involved in processes potentially linked to β-cell dysfunction, such as cell turnover, oxidative stress and ER stress." (PMID 33575641, 2020).
tumor (1 paper, 2022). "Ultimately, only two genes (UDP-glucose pyrophosphorylase 2 [UGP2], SDR39U1) were found to be significantly different from those in tumor and normal tissues." (PMID 35937991, 2022).
SDR39U1 also shares sentences with these, for which no sentence is quoted: atherosclerosis (1 paper); cancer (1); neurodegenerative disease (1).